PFN1 (profilin 1)
Diseases named in the same sentence as PFN1 in open-access papers (continued):
Sharing a sentence is not in itself a finding about the gene and the disease.
Immunodeficiency (1 paper, 2021). Failure of the immune system to protect the body adequately from infection, due to the absence or insufficiency of some component process or substance. "ABPs such as gelsolin, Tβ4, filamin, villin-1, gelsolin, profilin-1, SYNPO, and cortactin are abnormally expressed in certain inflammatory environments, where they inhibit or induce immunodeficiency inflammation." (PMID 34194957, 2021).
Intellectual disability (1 paper, 2016). "Several genes related to intellectual disability (Dcaf17, Myst4, Park2, Rbfox1) were found to be hypo-methylated in male pups, and genes (Pfn1, Cntnap1, Drp2) related to normal function of the nervous system were hypo-methylated in female pups from the HMFA group." (PMID 27199632, 2016).
kidney failure (1 paper, 2023). An acute or chronic condition that is characterized by the inability of the kidneys to adequately filter the blood. "In this study, we identified Pfn1 as indispensable in maintaining glomerular integrity — its tissue-specific loss in mouse podocytes resulted in severe proteinuria and kidney failure." (PMID 37847555, 2023). "Loss of podocyte-associated Pfn1 results in severe albuminuria, kidney failure, and death." (PMID 37847555, 2023). "Finally, Pfn1-KO mice exhibited biochemical evidence of kidney failure with elevated plasma creatinine when compared with littermate controls." (PMID 37847555, 2023).
Lissencephaly (1 paper, 2021). A spectrum of malformations of cortical development caused by insufficient neuronal migration that subsumes the terms agyria, pachygyria and subcortical band heterotopia. "PFN1 (Profilin-1) regulates actin polymerization and is associated with Miller–Dieker syndrome which is characterized by a lissencephaly." (PMID 35069108, 2021).
lysosomal storage disease (1 paper, 2022). A metabolic disorder caused by mutations in proteins critical for lysosomal function, including lysosomal enzymes, lysosomal integral membrane proteins, and proteins involved in the post-translational modification and trafficking of lysosomal proteins. "Similarly to OPTN and SQSTM1, also VCP and PFN1 share common roles in autophagic degradation raising the hypothesis of a common pathogenic mechanism affecting the formation and clearance of misfolded proteins in PDB, ALS and, more generally, in lysosomal storage diseases." (PMID 36035996, 2022).
meningioma (1 paper, 2023). A generally slow growing tumor attached to the dura mater. "On the other hand, up-regulation of PFN1 in high grade meningioma, could be connected with the stiffness of the extracellular matrix found in aggressive tumor tissues, which promotes proliferation." (PMID 37770851, 2023).
osteoporosis (1 paper, 2025). A condition of reduced bone mass, with decreased cortical thickness and a decrease in the number and size of the trabeculae of cancellous bone (but normal chemical composition), resulting in increased fracture incidence. "Notably, Profilin 1 expression was markedly elevated in the osteoporosis group, suggesting its potential as a valuable diagnostic indicator for OP." (PMID 40290428, 2025).
prostate tumor (1 paper, 2015). "Further, in prostate tumor cell line PC-3, cleavage of the C-terminal part of profilin 1 by up-regulated cathepsin X could lead to reduced clathrin-mediated endocytosis." (PMID 26325675, 2015).
renal fibrosis (1 paper, 2020). A final common manifestation of a wide variety of chronic kidney diseases characterized by glomerulosclerosis and tubulointerstitial fibrosis. "We assumed that renal fibrosis could be inhibited by downregulating the upstream regulator of Pfn1." (PMID 33162813, 2020).
retinal degeneration (1 paper, 2025). Degeneration of the retina. "Double overexpression of TDP-43 and mutant PFN1 exacerbated retinal degeneration, led to mislocalization of TDP-43 and increased neurodegeneration, while co-expression with WT PFN1 did not result in similar retinal degeneration." (PMID 40012679, 2025).
schizophrenia (1 paper, 2025). A major psychotic disorder characterized by abnormalities in the perception or expression of reality. "Our research indicates that neural cell adhesion molecule L1, integrin alpha-M, alpha-actinin-1, filamin-A and profilin-1 which are associated with cytoskeleton, synapse and immunity were preliminarily screened as candidate protein markers for schizophrenia." (PMID 41573035, 2025). "In our research, the differential proteins neural cell adhesion molecule L1, integrin alpha-M, alpha-actinin-1, filamin A, and profilin-1 are nominated as schizophrenia-associated candidates." (PMID 41573035, 2025). "However, there are relatively few studies on the association of the level of profilin-1 in peripheral blood with schizophrenia." (PMID 41573035, 2025). "This study suggests that proteins associated with the cytoskeleton, synapse, and immunity are related to schizophrenia, in particular neural cell adhesion molecule L1, integrin alpha-M, alpha-actinin-1, filamin A, and profilin-1, which are expected to be candidate protein markers for schizophrenia." (PMID 41573035, 2025).
sleep disorder (1 paper, 2018). A change from the patient's baseline sleeping pattern, in the hours slept and/or an alteration/dysfunction in the stages of sleep. "Therefore, PFN1 may serve as a potential useful biomarker for sleep disorders and may also represent an important therapeutic target for the treatment or prevention of the CSD-related cardiovascular diseases." (PMID 30235220, 2018). "Expression of four proteins including PKM, CLU, KNG1 and PFN1 were changed by CSD and these proteins can potentially serve as biomarkers for sleep disorders." (PMID 30235220, 2018).
subarachnoid hemorrhage (1 paper, 2012). A serious neurological disorder characterized by intracranial hemorrhage into the subarachnoid space. "For example, ROCK inhibitors (e.g. fasudil), which are expected to up-regulate PFN1 activity, are already in clinical use to reduce vasospasm in the setting of subarachnoid hemorrhage." (PMID 22479341, 2012).
type 2 diabetes (1 paper, 2018). "We also identified seven genes (Sardh, Slc39a7, Pfn1, Arg1, Cth, Sod1 and P4hb) in the liver and one gene (Fabp4) in the adipose tissue that may be associated with type 2 diabetes in gerbils." (PMID 29394254, 2018).
urinary bladder urothelial carcinoma (1 paper, 2016). "Further studies on signaling pathway demonstrated that ethanol extract treatment might inhibit urinary bladder urothelial carcinoma cell proliferation through restriction of PTEN/AKT/mTORC1 pathway via profilin 1 up-regulation." (PMID 26955879, 2016).
viral infection (1 paper, 2022). "Platelet activation involves, amongst many other pathways, profilin 1, cofilin, and the actin cytoskeleton, and viral infection can temporarily lower platelet counts." (PMID 36366577, 2022). "Low PFN1, CFN1, and ACTB levels in individuals with low adjusted seroconversion might indicate a recent viral infection (prior to receiving the vaccine) which weakened the immune response." (PMID 36366577, 2022).
tumor (67 papers, 2005 to 2026). "Pfn1 loss has been associated with increased cancer cell proliferation, migration, and invasion across multiple tumor types." (PMID 40710368, 2025). "Profilin 1—encoded by PFN1—is a small actin-binding protein with a tumour suppressive role in various adenocarcinomas and pagetic osteosarcomas." (PMID 36599901, 2023). "Caliper measurements showed that both S71A and S71D mutations abolish the antitumor effect of Pfn1 and caused an additional increase in tumor growth compared to the GUS control." (PMID 34235154, 2021). "In accord with these data, clinical correlation findings further revealed lower Pfn1 expression associated with lower nuclear grade tumours and longer RFS of BC patients." (PMID 30318519, 2018). "Proteome array analysis of the secretome of T24MshPFN1 and T24MshSCR cells was performed to investigate the expression of known tumor-associated secreted factors following PFN1 downregulation." (PMID 27683119, 2016). "The aim here was to mutate residues at the C-terminus of profilin 1 to assess their contribution to profilin 1 processing, clathrin binding, clathrin-mediated endocytosis and tumor cell migration and invasion." (PMID 26325675, 2015). "High expression of Profilin-1 (PFN1-a regulator of actin polymerization) was associated to tumor infiltration and lymph node metastasis." (PMID 26635609, 2015). "This was confirmed by the weights of dissected tumors, strongly suggesting a decrease in tumor cell growth caused by Pfn1 overexpression." (PMID 25103363, 2014). "In vitro and in vivo experiments showed that loss of Pfn1 expression contributed to cell proliferation and tumor growth." (PMID 25103363, 2014). "We previously identified PFN1 as a huntingtin aggregation inhibitor, and others have implicated it as a tumor-suppressor." (PMID 22479341, 2012). "Profilin 1 over-expression has been reported to cause cell proliferation inhibition, apoptosis induction and tumor suppression." (PMID 21933383, 2011). "In addition, genome sequencing of OS/PDB tumour biopsies with PFN1 loss of heterozygosity shows complex genome rearrangements, including chromothripsis." (PMID 36599901, 2023). "Given that multiple copies of the same parental PFN1 allele are observed in 8/10 tumours with LOH of PFN1, it is more likely that loss of PFN1 occurred before WGD rather than through multiple chromosomal losses following WGD, although we cannot fully rule out either possibility." (PMID 36599901, 2023). "The underlying mechanisms of tumor suppressor effects of profilin 1 were integrin β1/FAK." (PMID 33163494, 2020). "The mechanism involves the spatial regulation of profilin-1, a protein that acts as a tumor suppressor when localized to the nucleus." (PMID 39882192, 2025). "A third lncRNA, HLA-F-AS1, further promotes the differentiation of M2 macrophages, by sponging the tumor-suppressive miR-375 to upregulate PFN1 levels in macrophages." (PMID 41154428, 2025). "In triple-negative breast cancer, elevated levels of PFN1 correlate with tumor progression and metastasis." (PMID 40981267, 2025). "Loss of function of PFN1 was previously detected in OS/PDB26, an aggressive tumour of mesenchymal origin." (PMID 36599901, 2023). "Numerous studies have confirmed that PFN1 involved in tumor proliferation, apoptosis, stemness, immune response and metastasis." (PMID 35586060, 2022). "The involvement of PFN1 in carcinogenesis is likely to be determined not only by the histotype and localization of the tumor, but also by its relationship with other proteins." (PMID 37226274, 2022). "Studies showed that the endogenous over-expression of profilin 1 resulted in a tumor-suppressive nature." (PMID 35164374, 2022). "Results showed that PFN1 was highly expressed in NSCLC tissues compared with adjacent non-tumor tissues." (PMID 35586060, 2022).
tumor (continued). "Several mechanisms have further link CatX to tumor progression, including bypassing senescence, modulating adhesion and migration of tumor cells through cleavage of integrin receptors and profilin-1, and inducing epithelial-mesenchymal transition." (PMID 34989869, 2022). "PFN1 has been proposed as a tumour suppressor in several cancers, with reduced expression identified in breast, liver, bladder and pancreatic cancers." (PMID 35440627, 2022). "Considering these lines of evidence, we suggest that the upregulation of PFN1 in serum EV samples isolated from overt DFTD devils likely originates from DFTD tumor cells." (PMID 35422813, 2022). "CatX enhances tumor cell migration and invasion through interaction with integrin receptors or cleavage of the C-terminal part of the tumor suppressor protein profilin-1." (PMID 34989869, 2022). "Taken together, our data in this paper demonstrated that Ser71 is a bona fide phosphorylation site of Pfn1 capable of inhibiting its actin-binding ability, preventing its nuclear export, and influencing its tumor-inhibitory functions." (PMID 34235154, 2021). "Dissection of the functional influences of subcellular localization further indicated that while tumor inhibition by Pfn1 is driven largely by its nuclear activities, apoptosis-sensitizing effect depends on its cytoplasmic localization." (PMID 34235154, 2021). "This indicates that, rather than functioning as an on/off switch, reversible phosphorylation and dephosphorylation at Ser71, causing dynamic actin dissociation and rebinding, are required for Pfn1 to inhibit tumor growth." (PMID 34235154, 2021). "Our recent work suggested that tumor growth inhibition by Pfn1 is mediated at least in part by its nuclear function in repressing SEC-dependent transcription of pro-cancer genes including c-MYC." (PMID 34235154, 2021). "We have found in prior and recent studies that PLP-binding is important for the tumor-inhibitory function of Pfn1, at least partially due to the direct interaction of nuclear Pfn1 with ENL, a PLP-containing protein, in the SEC complex." (PMID 34235154, 2021). "Paradoxically, Pfn1 also shows anti-tumor and anti-metastatic activities for various types of cancer (breast, pancreatic, and liver)." (PMID 34235154, 2021). "By classifying MPNST patients based on profilin 1 expression (high, 2–3 scores; low, 0–1 scores), clinicopathological correlation analyses revealed profilin 1 expression negatively correlated with large tumor size (p = 0.047)." (PMID 33163494, 2020). "In this study, we demonstrate that lower Pfn1 expression correlates with lower nuclear grade (NG: an indicator of growth-aggressiveness of tumour cells) of BC cells and longer relapse-free survival (RFS) of BC patients." (PMID 30318519, 2018). "Overall, these data demonstrate that Pfn1 downregulation can potentially impact oncogenic and tumour-suppressor pathways in BCC." (PMID 30318519, 2018). "For both luminal A (ER and/or PR+, HER2−) and triple-negative (ER−, PR− and HER2−) BC, the average Pfn1 immunoreactivity was significantly lower in low NG tumours than higher nuclear grade tumours." (PMID 30318519, 2018). "In our opinion the established link between PrPc and PFN-1 deserves a special attention given PFN-1 role in tumor suppression on one side and PrPc role as a promotor of cancer cell invasiveness on the other." (PMID 28102851, 2017). "IHC analyses showed a similar PFN1 expression pattern in human BC and mouse xenograft tissues, with PFN1 levels decreasing with tumor progression." (PMID 27683119, 2016). "Collectively, mRNA sequencing confirmed the down-regulation of known tumor inducers and up-regulation of tumor suppressors, also supported by the secretome analysis, following PFN1 suppression." (PMID 27683119, 2016).
tumor (continued). "In agreement with the HCC cell data, there was an increase in the mRNA levels and protein expression levels of PFN1 in the lung tumor nodules from GUTK-treated mice in a dose-dependent manner." (PMID 27494863, 2016). "Along the same lines, herein, we show that suppression of PFN1 inhibits T24M cell migration and adhesion in vitro and tumor establishment in vivo." (PMID 27683119, 2016). "As shown, PFN1 levels decreased with tumor progression (quantified optical absorbance of 155.5±25.0 au at 30 days compared to 102.5±7.4 au at 60 days, p<0.0001 Student's t-test)." (PMID 27683119, 2016). "PFNI has been implicated in cancer, including pancreatic, gastric and breast cancers, with frequently contradicting results; supporting in cases that PFN1 induces tumor establishment or in others, suppressing progression and metastasis." (PMID 27683119, 2016). "Its molecular target in tumor cells is profilin 1, a known tumor suppressor and regulator of actin cytoskeleton dynamics." (PMID 26325675, 2015). "Profilin 1 has recently been identified as a target for cathepsin X carboxypeptidase activity in tumor cells." (PMID 26325675, 2015). "Cathepsin X cleaves off the C-terminal Tyr139 of profilin 1, affecting binding of poly-L-proline ligands and, consequently, tumor cell migration and invasion." (PMID 26325675, 2015). "Pfn1 protein expression in PDAC specimens was analyzed by immunohistochemistry using a tissue microarray (TMA) containing PDAC tumor tissue and corresponding normal tissue samples from 72 patients." (PMID 25103363, 2014). "In conclusion, profilin 1 has been identified as an important molecular target of cathepsin X in tumor cells." (PMID 23326535, 2013). "Higher levels of profilin 1 act to inhibit tumor progression, and its down-regulation has been reported in different types of adenocarcinoma (breast, hepatic, pancreatic)." (PMID 23326535, 2013). "As tumor suppressor, profilin 1 was reported many times to inhibit cell motility and matrigel invasivness, but exact mechanism has not been discovered yet." (PMID 23326535, 2013). "PFN1 is also a putative tumor suppressor, and has been shown to inhibit tumor cell growth and metastasis in several cancer models." (PMID 22479341, 2012). "Certainly, profilin 1 is thought to be a tumor suppressor: it is downregulated in aggressive forms of cancer compared to normal cells and inhibits cell functions required for metastasis including proliferation and migration." (PMID 22359590, 2012). "Among them, five proteins, including cyclophilin-A, S100A4, profilin-1, thymosin beta 4 and 10, which previously correlated to tumor progression, were identified at the progressive stage." (PMID 18796163, 2008). "Interestingly, we recently reported suppression of STAT1 expression in a tumor microenvironment when Pfn1 is overexpressed in EC." (PMID 37781098, 2023). "Accordingly, WGD events and LOH at the PFN1 locus were frequently detected in OS/PDB tumours." (PMID 36599901, 2023). "Thus, our results indicate that Profilin 1 has a role in regulating cell division, and its inactivation triggers mitotic defects, one of the major mechanisms through which tumour cells acquire chromosomal instability." (PMID 36599901, 2023). "We therefore hypothesised that the reduction of Profilin 1 observed in OS and adenocarcinomas underpins tumour onset due to mitotic errors." (PMID 36599901, 2023). "PFN1 expression was upregulated in tumor and metastatic tissues compared with that in normal lung and adjacent non-tumor tissues, suggested that PFN1 may associated with NSCLC metastasis." (PMID 35586060, 2022). "Correlations between the number of CTCs and immune cells expressing CAP1 and PFN1 may reflect the peculiarities of the molecular mechanisms of the tumor-host relationship in the pathology." (PMID 37226274, 2022). "The involvement of PFN1 in the processes of tumor progression is still being studied." (PMID 37226274, 2022).